IL1B (interleukin 1 beta)
Diseases named in the same sentence as IL1B in open-access papers (continued):
Sharing a sentence is not in itself a finding about the gene and the disease.
periodontitis (continued). "Decreased LCs and increased pDCs were observed in the gingiva of periodontitis patients, accompanied by increased expression of proinflammatory cytokines IL-1β, IFN-α, and IFN-γ and suppressed expression of anti-inflammatory cytokines IL-1045." (PMID 41015585, 2025). "To further mimic a chronically inflamed environment such as that apparent in periodontitis, we added 10 ng/mL IL-1β to osteogenesis and osteoclastogenesis cultures for the duration of the experiment." (PMID 40136507, 2025). "There was a significant decrease in salivary Metrnl concentrations of the periodontitis group and salivary Metrnl and IL-1β concentrations were significantly correlated with periodontal clinical parameters (negative and positive, respectively)." (PMID 39964474, 2025). "According to the results of the post hoc Bonferroni test, the mean salivary and GCF levels of TNF-α and IL-1β in healthy individuals were significantly lower than those with periodontitis (P<0.05) and gingivitis (P<0.05)." (PMID 40265034, 2025). "Patients with severe periodontitis exhibit significantly elevated levels of pro-inflammatory mediators—namely IL-1β, TNF-α, and IL-6—in both serum and saliva." (PMID 40869031, 2025). "In vivo studies showed a protective effect against P. gingivalis-induced periodontitis in rats by reducing bacterial load and regulating IL-1β and TNF-α production." (PMID 41567672, 2025). "According to the post hoc Bonferroni test results, the mean salivary and GCF levels of TNF-α and IL-1β in healthy individuals were significantly lower than those with periodontitis and gingivitis." (PMID 40265034, 2025). "Salivary IL-1β concentrations were significantly higher in both the gingivitis and periodontitis groups when compared to healthy group (p < 0.001)." (PMID 39964474, 2025). "Elevated IL-1β levels in the saliva of patients with gingivitis and periodontitis, compared to the healthy group, highlight the cytokine’s role in gingival and periodontal inflammation, supporting previous studies." (PMID 40265034, 2025). "In periodontitis, the immune system overreacts, producing too many inflammatory signals, such as interleukin-6 (IL-6), interleukin-1beta (IL-1β), and tumor necrosis factor-alpha (TNF-α)." (PMID 41333792, 2025). "Lipopolysaccharides and other byproducts from periodontitis elevate cerebral pro-inflammatory mediators (IL-1β, TNF-α, IL-6), which promote amyloid accumulation, leading to neurodegeneration and Alzheimer’s disease." (PMID 40433667, 2025). "Its anti-inflammatory properties help lower the levels of pro-inflammatory cytokines such as TNF-α, IL-1β, and IL-6, which are crucial in driving tissue damage in periodontitis." (PMID 40530190, 2025). "Protein analysis of gingival tissue ex vivo showed ligature-induced periodontitis (LIP) induced higher pro-inflammatory IL-1β levels compared to the unligated controls and decreased IL-1β in A2aR-agonist-treated mice compared to non-treated mice." (PMID 40862745, 2025). "ADMA levels in gingival crevicular fluid (GCF) are significantly higher in individuals with periodontitis and positively correlate with IL-1β and clinical periodontal parameters." (PMID 41328144, 2025). "The results revealed an increased proportion of TREM1+ Mφ, characterized by the high IL1B expression, in periodontitis, eosinophilic esophagitis (EoE), IBD, and perianal fistulizing Crohn’s disease (Perianal-CD)." (PMID 41318555, 2025). "Seven markers (Interleukins [IL]‐1α, IL‐1β, IL‐8, matrix metalloproteinase‐13, osteoactivin, osteoprotegerin and C‐reactive protein) were significantly upregulated in periodontitis patients as compared to healthy controls." (PMID 40464289, 2025). "In this study, we focused on IL-1β and IL-6, which are central inflammatory mediators in periodontitis, to provide a representative assessment of the inflammatory response alongside salivary cortisol." (PMID 40843742, 2025).
periodontitis (continued). "These properties of NLRP3 and IL-1β highlight the growing interest in their study to elucidate the link between periodontitis and hypertension, as well as their potential as preclinical biomarkers for the risk of developing both conditions." (PMID 40572711, 2025). "Recently, one study showed that Gal-3 and IL-1β were detected in periodontally healthy, gingivitis, and periodontitis participants." (PMID 40429343, 2025). "As we have observed in THP-1 derived macrophages, it is well established that NLRP3 and AIM2 are upregulated in saliva, periapical lesions and gingival tissues of periodontitis patients, driving an increase in IL-1β secretion." (PMID 40490723, 2025). "This ferroptosis induction leads to an increase in the levels of proinflammatory cytokines, including IL-1β, IL-6, and IL-8, thereby exacerbating the progression of periodontitis." (PMID 40541947, 2025). "Consistently, increasing concentrations of chemokines such as TNFα, IL1β and CXCL8 in the gingival crevicular fluid and peri-implant crevicular fluid are associated with the severity of periodontitis and peri-implantitis." (PMID 40565042, 2025). "As with reports of increased TNF-α and IL-1β levels in gingival tissue and serum from patients with periodontitis, the present study also showed higher levels of TNF-α and IL-1β in the L group." (PMID 39941567, 2025). "By integrating cortisol with staging and grading of periodontitis and concurrently evaluating IL-1β and IL-6, we offer new insights into the complex biological underpinnings of stress-related periodontal pathology." (PMID 40843742, 2025). "VNS treatment effects on ligature-induced inflammation in periodontitis rats was investigated by detecting the IL-1β level." (PMID 41191726, 2025). "In one study, patients with severe periodontitis were found to have higher salivary concentrations of IL-1β and MMP-8." (PMID 40528176, 2025). "Peripheral neutrophils from patients with periodontitis release increased amounts of IL-1β, IL-8, IL-6, and tumor necrosis factor (TNF)-α upon stimulation with periodontal pathogens." (PMID 40572711, 2025). "To further explore the potential KEGG pathways in which these genes are involved in the shared pathogenic mechanisms of AAA and periodontitis, we performed GSEA on IL1B, PTGS2, and SELL." (PMID 40857330, 2025). "Studies have also shown that genistein significantly reduced the expression levels of TNF‐α, IL‐6, IL‐1β, and IL‐17a in the gingival tissue of periodontitis mice and reduced the damage of inflammatory factors to periodontal tissue." (PMID 40761494, 2025). "Considering that IL-1β is one of the signaling pathways of rheumatoid arthritis and periodontitis, a therapeutic option is the use of an IL-1 receptor antagonist (IL-1RA) that prevents IL-1β signaling." (PMID 40136507, 2025). "In periodontitis, IL1B is a key effector of the host response to periodontal pathogens (e.g., Porphyromonas gingivalis)." (PMID 40857330, 2025). "The ELISA results showed the NF-κB signaling related inflammatory cytokines such as TNFa, IL-1β, and IL-6 increased in the Bmal1- periodontitis group." (PMID 40008712, 2025). "Among them, IL-1β and IL-6 have shown particular promise in distinguishing between health, gingivitis, and periodontitis." (PMID 41155385, 2025). "Ligature‐induced periodontitis and diabetic models: liraglutide decreases bone loss, improves microarchitecture, and lowers IL‐6, TNF‐α, and IL‐1β." (PMID 41328144, 2025). "In a study of 189 subjects, severe periodontitis patients showed gingival crevicular fluid IL-1β levels of 61.04 ± 41.41 pg/mL, significantly higher than controls." (PMID 40869031, 2025). "A key component of the inflammatory response in periodontitis is the production and release of IL-1β, a pro-inflammatory cytokine." (PMID 40137780, 2025). "Since IL‐1β is a pivotal inflammatory cytokine in periodontitis, we first established its effect on osteoclastogenesis." (PMID 41368333, 2025).
periodontitis (continued). "Increased levels of IL-1β, a precursor of other cytokines in the inflammatory process, play an important role in the onset and development of periodontitis pathogenesis." (PMID 39964474, 2025). "Several studies have shown that levels of IL-1β, IL-6, IL-8, and IL-17A are elevated in periodontal tissues of patients with periodontitis compared to healthy controls, driving disease progression." (PMID 41274884, 2025). "Kinney et al23 observed significant decreases in IL-1β levels in the periodontitis group at 8, 10, and 12 months, in the gingivitis group at 8 and 10 months, and in the healthy group at 10 months compared to baseline." (PMID 40265034, 2025). "We identified a pro-inflammatory signature in GCF of T1DM individuals with periodontitis, marked by elevated IL-1β, IL-6, IL-8, and IL-17A, suggesting activation of both innate and adaptive immune pathways." (PMID 41280935, 2025). "TNF‐α and IL‐1β are pro‐inflammatory cytokines that are involved in the initiation and progression of periodontitis and have been used to establish models of inflammatory environments." (PMID 39572253, 2025). "From healthy to severe periodontitis, the expression of IL-1β, IL-6, IL-8, TNF and MMP-9 gradually increased, but the E–P interaction scores remained constant, suggesting a persistent epigenetic regulatory footprint." (PMID 40902506, 2025). "The GCF total amount of IL-1β was significantly higher in the periodontitis group compared to the gingivitis group (p < 0.001)." (PMID 39964474, 2025). "The level of IL-1β in gingivitis sites was significantly higher than that in healthy sites (p < 0.001), but lower than in periodontitis sites (p < 0.001)." (PMID 41303313, 2025). "For instance, previous research has shown that IL-1β alone exhibits an area under the curve (AUC) value of 0.88, with a 90% sensitivity and 76% specificity in distinguishing periodontitis from healthy subjects." (PMID 40283051, 2025). "Their results indicated higher IL-1β levels in the gingivitis group during the second month than in the periodontitis groups (mild and moderate to severe)." (PMID 40265034, 2025). "In the immune response to periodontitis, dendritic cells infected by Pg activate related SASPs, such as IL-1β, IL-6, and IL-8, which ultimately accelerate the progression of periodontitis." (PMID 40801798, 2025). "Patients with severe periodontitis exhibit significant increases in the expression of interleukin-1β (IL-1β), tumor necrosis factor-α (TNF-α), nod-like receptor protein 3 (NLRP3), and their absence in melanoma 2 (AIM2) inflammasomes in the gingival tissues." (PMID 38921772, 2024). "Accordingly, salivary IL-1β has been reported to exhibit a potential to distinguish periodontitis from periodontal health with varying sensitivity (54%–88%) and specificity (52%–100%)." (PMID 39445112, 2024). "In a ligature-induced periodontitis model, compared with wild-type mice,NLRP3-knockout mice exhibited decreased loss of alveolar bone, reduced release of IL-1β and impaired differentiation of osteoclasts." (PMID 38596842, 2024). "MMP-8 combined with IL-1β can distinguish between periodontal health and periodontitis, even in patients with systemic inflammatory diseases such as type 2 diabetes mellitus." (PMID 39554809, 2024). "A recent meta-analysis indicated that early periodontitis diagnosis accuracy significantly increases when detecting IL-1β alongside other biomarkers in saliva." (PMID 39554809, 2024). "GF and periodontal ligament fibroblasts facilitate the inflammatory cascade in periodontitis, producing pro-inflammatory cytokines, like IL-1β, IL-6 and TNF-α." (PMID 39252697, 2024). "Hypothyroid patients, particularly those with periodontitis, had considerably greater serum levels of IL-1β than the control group (healthy individuals)." (PMID 39063437, 2024). "Combining salivary biomarkers such as MMP-8 and IL-1B can prove to be a valuable key to diagnose gingivitis and periodontitis." (PMID 38086426, 2024).
periodontitis (continued). "IL-1β has been reported to be elevated in serum, saliva, and gingival crevicular fluid of periodontitis patients." (PMID 39445112, 2024). "Several studies have shown that MMP-8 and IL-1β are the most reliable markers of persistent periodontitis, and the Helsinki group has developed point-of-care tests (PerioSafe®, ImplantSafe®) to assess salivary MMP-8 levels." (PMID 39275315, 2024). "In the current study, analysis of the data showed that salivary IL-1β, IL-10, and IL-1β/IL-10 ratio had high accuracy in differentiating periodontal health from periodontitis." (PMID 39445112, 2024). "IL-1β concentrations were higher in all experimental periodontitis groups compared to the healthy control group." (PMID 38359268, 2024). "In saliva, MMP-8 combined with IL-1β, and IL-6, are excellent for detecting periodontitis and identifying non-periodontitis." (PMID 39554809, 2024). "An online differential expression analysis conducted using OralExplorer revealed several genes that were significantly upregulated in all six periodontitis-related datasets, including IL-1β, SRGN, CXCR1, FGR, ARHGEF2, and PTAFR." (PMID 38491529, 2024). "Activation of NF-κB signaling pathway can enhance osteoclast differentiation and exacerbate periodontitis by increasing the expression of IL-1β and various inflammatory factors." (PMID 38218802, 2024). "Regarding IL-1β, we detected lower levels in cases with periodontitis compared with controls (0.1 in cases and 0.2 pg/mL in controls)." (PMID 39101637, 2024). "Proinflammatory cytokines, such as IL-1α, IL-1β, IL-6, IL-8, TNF-α and TNF-β, are associated with osteoclastogenesis, a key process leading to clinical periodontitis outcomes and periodontitis-associated inflammatory diseases." (PMID 38396821, 2024). "The aim of this research is to assess the effectiveness of 0.2% HA gel on periodontal parameter, quantity ofPgandFn, and the levels of proinflammatory cytokine, IL-1β, and anti-inflammatory cytokine, IL-10, in DM patients with periodontitis." (PMID 39074834, 2024). "Data obtained from qRT-PCR analyses of gingival tissue showed that salicin treatment significantly inhibited the expression of proinflammatory factors in the WT-periodontitis mice, including Il-1β, Tnf-α, Il-17." (PMID 38605968, 2024). "Suppression of the inflammatory response is one of the guidelines for the treatment of periodontitis; IL-1β and TNF-α are two pro-inflammatory cytokines active in periodontitis." (PMID 39445594, 2024). "In studies conducted for this purpose, significant increases in blood IL-1β levels were observed in most patients with chronic periodontitis." (PMID 39012553, 2024). "Clinical evidence confirms that patients with periodontitis exhibit elevated levels of pro-inflammatory mediators, including IL-1β, IL-6, TNFα, and C-reactive protein (CRP), as well as increased neutrophil counts in peripheral blood when compared to controls." (PMID 39737182, 2024). "Our study showed that the IL-1B levels were found to be higher in the periodontitis group than in the healthy control and gingivitis groups." (PMID 38086426, 2024). "The IL-1β/IL-10 ratio in saliva exhibits a valuable potential for diagnosing periodontitis and in discriminating periodontitis stability." (PMID 39445112, 2024). "A cascade of inflammatory proteins and enzymes is directly involved in periodontitis’ osteoclastogenesis, including proinflammatory cytokines such as IL-1β, IL-6, IL-11, IL-17, and TNF-α (point 6)." (PMID 38792574, 2024). "For instance, studies on green tea extract (Camellia sinensis) have demonstrated its ability to reduce levels of proinflammatory cytokines such as TNF-α and IL-1β in periodontitis models." (PMID 39539670, 2024). "Throughout the experimental study, the PRP on days 7 and 30 attenuated the inflammatory reaction of periodontitis by decreasing the expression of IL-1β in both the endothelium and inflammatory cells in the periodontal tissue." (PMID 40952876, 2024).
periodontitis (continued). "In this study, the IL-1β/IL-10 ratio exhibited high sensitivity and specificity for potentially discriminating periodontitis from healthy groups as well as for distinguishing unstable from stable periodontitis groups." (PMID 39445112, 2024). "The mice with periodontitis had impaired cognitive function and increased amyloid-beta (Aβ) deposition in the brain, along with elevated pro-inflammatory cytokines (IL-1β and TNF-α)." (PMID 39044527, 2024). "Periodontitis results in elevated systemic levels of C- reactive protein, IL-1β, IL-6, IL-8, and TNF-α." (PMID 39917647, 2024). "Increased salivary levels of NLRP3, ASC, and IL-1β were also observed in systemic healthy patients with periodontitis, and diabetic patients with periodontitis, when compared with healthy periodontal patients." (PMID 38817019, 2024). "The test also revealed that IL-1β levels were higher in the periodontitis group compared with the healthy control and gingivitis group." (PMID 38086426, 2024). "From our data, we observed a classical pro-inflammatory profile with elevated levels of IL-1β and IL-6 in periodontitis patients." (PMID 39125970, 2024). "Local injection of icariin can attenuate the inflammatory process in minipig periodontitis models, and levels of the pro-inflammatory cytokines IL-1β and IFN-γ were lower in the icariin group than in the control group." (PMID 37396128, 2023). "Existing studies indicate that the NLRP3/IL-1β signaling pathway played a crucial role in the occurrence and development of periodontitis." (PMID 37900318, 2023). "A reduction in IL-1β levels was observed after administration of this probiotic strain in animals with ligature-induced periodontitis." (PMID 36305963, 2023). "In the patients with grade B periodontitis, there was only a moderate statistically significant positive correlation between the biomarker IL-1β and the PI percentage (r = 0.604; p < 0.05) and the BOP percentage (r = 0.572; p < 0.05)." (PMID 36769650, 2023). "The higher IL‐1β GCF levels found in periodontitis sites and the presence of three red complex periodontal pathogens and IL‐1B(3954)‐SNP compared with healthy sites within the same individuals." (PMID 36414019, 2023). "At doses ranging from physiologically healthy to those found in chronic periodontitis, IL-1β plays a dual role in the osteogenesis of PDLSCs." (PMID 36902030, 2023). "It should be pointed out that periodontitis fosters a proinflammatory microenvironment, and the levels of IL-1β, IL-4, IL-10, and IL-17A were significantly higher in diseased sites than healthy sites in the same oral cavity from periodontitis patients." (PMID 36949458, 2023). "In contrast, remarkably elevated IL‐1β level was detected in the serum of patients with mild and severe periodontitis." (PMID 37506160, 2023). "There was a positive correlation of PD, PI, GI and BL with IL-1β levels, similarly to periodontitis." (PMID 37232785, 2023). "gingivalis virulence factors arsenal, promoting an inflammatory microenvironment characterized by cytokine production (TNF-α, IL-1β, IL-6), prostaglandins, and metalloproteinases (MMPs) that foster the tissular destruction characteristic of periodontitis." (PMID 36897441, 2023). "We reported that elevated mRNA and protein levels of IL‐1β and GSDMD, decreased levels of Synoviolin mRNA and protein, and decreased ubiquitination of GSDMD were associated with periodontitis." (PMID 37506160, 2023). "Both periodontitis and colon cancer have been associated with elevated MDSC levels, and increased levels of TNF-α, IL-1β, IL-6 and MMP-9 are also common factors in both conditions." (PMID 38029267, 2023). "As expected, the mRNA levels of TNF, IL‐6, and IL‐1β dramatically increased in periodontitis mice as compared with control NT mice, while NAC‐S2 treatment significantly suppressed their expression levels in periodontitis mice." (PMID 37647428, 2023).